DEK (DEK proto-oncogene)
Diseases named in the same sentence as DEK in open-access papers (continued):
Sharing a sentence is not in itself a finding about the gene and the disease.
cancer (continued). "The inverse in transcriptional regulation of genes between AD and cancer gives more credence to the notion that DEK loss could be related to AD, given DEK’s predominant role as an oncogene when overexpressed in peripheral tissues." (PMID 36275000, 2022). "In addition to such biological consequences, the extent of metabolic deregulation caused by DEK overexpression is similar to reported changes in cancer versus normal tissue." (PMID 28558019, 2017). "Notably, many studies have reported that DEK implicated in several signaling pathways in tumor cells and played important role in cancer progression." (PMID 24650035, 2014). "DEK proto‐oncogene (DEK), an oncogene, is highly expressed in most human tissue cells and is overexpressed in developing cancers." (PMID 39668431, 2025). "Supporting this, DEK overexpression is frequently observed in cancer cells with abnormal cell proliferation and micronucleus formation." (PMID 39984731, 2025). "This case underscores the potential for DEK::AFF2 carcinoma to occur throughout the entire respiratory tract, including the larynx." (PMID 40299135, 2025). "DEK is an oncogene that plays a key role in hetero- chromatin regulation and is consistently upregulated in various cancer types including both HPV-positive and HPV-negative head and neck SCC." (PMID 38429827, 2024). "The other morphologic mimics of MEC, including SCC, and DEK::AFF2 fusion-associated papillary SCC, were renamed “DEK::AFF2 carcinomas”." (PMID 38429827, 2024). "As our understanding of these tumors evolves, new entities, such as DEK::AFF2 carcinoma, are being identified, further expanding the spectrum of sinonasal malignancies." (PMID 39766144, 2024). "Specifically, germane to the present study, HSPGs play a role in internalization of the oncoprotein DEK, a protein that is upregulated in a variety of cancers." (PMID 37550562, 2023). "DEK expression levels increase significantly from normal to cancer cells, hence raising the possibility of using DEK as a tumor marker." (PMID 37550322, 2023). "This work combines and refines our previous data on DEK as a factor essential for heterochromatin integrity and facilitating replication under stress, and delineates an avenue of further study for unraveling the contribution of DEK to cancer development." (PMID 37997922, 2023). "It is well established that the DEK protein is overexpressed in highly proliferating cells, such as cancer cells, and can alter the chromatin topology." (PMID 38026229, 2023). "Recently, overexpression of DEK was found to be positively correlated with tumorigenesis and metastasis in various cancers." (PMID 35742899, 2022). "DEK and miR-5100 play critical roles in many steps of cancer initiation and progression and are directly or indirectly regulated by most promoters and repressors." (PMID 35563178, 2022). "DEK plays a crucial role in many steps of cancer initiation and progression and is directly or indirectly regulated by most promoting and repressing factors." (PMID 35563178, 2022). "A global investigation of the ubiquitylome in a prostate epithelial cell model expressing cancer-associated SPOP alterations indicates that DEK and TRIM24 are essential substrates, and that DEK stabilization promotes cell invasion." (PMID 35682963, 2022). "IHC results showed that DEK was highly expressed in cancer tissues of patients compared with normal tissues." (PMID 35563178, 2022). "DEK facilitates the tumorigenesis of different types of cancer cells by promoting cell proliferation and modulating cell cycle transition, as well as inhibiting cell apoptosis and senescence." (PMID 35769815, 2022). "Western Blot results and quantitative analysis showed that DEK was highly expressed in cancer tissues." (PMID 35563178, 2022). "The immunoprofile of DEK::AFF2 carcinomas is in accordance with a squamous phenotype, being diffusely p63 and p40 positive." (PMID 35326613, 2022).
cancer (continued). "Together, this is the first report identifying an oncogenic role for DEK expression within cancer cells through a mechanism involving the regulation of the tumor microenvironment and the tumor-immune response." (PMID 32708944, 2020). "Using in vitro models, we demonstrate DEK expression in cancer cells promotes the M2-like polarization of bone marrow derived macrophages (BMDM)." (PMID 32708944, 2020). "Substantial work has previously demonstrated that DEK expression in cancer cells promotes proliferation through multiple pathways, including Wnt signaling, and is required for DNA damage repair." (PMID 32708944, 2020). "DEK also helps to maintain the cancer stem cell population, and, at least when present as a fusion protein with CAN in AML, it can induce the transformation of normal stem cells." (PMID 32656741, 2020). "Subsequently, DEK overexpression was reported in many cancers, thus DEK itself is considered to be an oncoprotein." (PMID 32656741, 2020). "Dysregulation of DEK is also thought to promote tumorigenesis and sustained proliferation of cancer stem cells." (PMID 32656741, 2020). "We summarized the current reports implicating DEK as a proto-oncogene in SCC and dysplastic disorders and discussed the potential of DEK as a therapeutic target for the selective targeting of cancer cells, especially SCC." (PMID 32656741, 2020). "DEK regulated cellular invasion has been partially attributed to β-Catenin activation in the cancer cells." (PMID 32257110, 2020). "Further, cancer cells overexpressing DEK often exhibit heterochromatin instability and marked dysregulation of the epigenome." (PMID 32656741, 2020). "A continuously increasing number of studies link DEK overexpression to cancer development, pinpointing DEK as a “bona fide” oncogene." (PMID 31408463, 2019). "DEK is a highly conserved chromatin-bound protein whose upregulation across cancer types correlates with genotoxic therapy resistance." (PMID 28317934, 2017). "Taken together, these data support a scenario whereby overexpression of the human DEK oncogene reprograms keratinocyte metabolism to fulfill energy and macromolecule demands required to enable and sustain cancer cell growth." (PMID 28558019, 2017). "We also found that DEK promoted cancer cell angiogenesis and metastasis by activating the PI3K/AKT/mTOR pathway." (PMID 29228721, 2017). "The DEK oncogene is overexpressed in various cancers and overexpression of DEK correlates with poor clinical outcome." (PMID 26988756, 2016). "Recent studies indicate that DEK plays crucial roles in numerous cancers, while its function in HCC is rarely elucidated." (PMID 27057626, 2016). "DEK is important in various cancer cell types, including breast and bladder cancer, melanoma, and most recently, HNSCCs." (PMID 26527316, 2015). "Further comparative gene expression profiling analysis of DEK-knockdown and control PC-3 cells demonstrated that a number of genes involved in the cell cycle and cancer metastasis were differentially expressed after DEK knockdown." (PMID 25544761, 2015). "The multifunctionality of DEK in immune cells and cancer cells suggests a paradoxical outcome in tumor biology." (PMID 26425120, 2015). "Similar results were obtained with primary human keratinocytes, implicating DEK as a cancer and primary cell survival factor." (PMID 25340858, 2014). "Meanwhile, the strongly positive rate of DEK protein was higher in cancer cases with serosal invasion (50.00%, 26/52) than in those with no serosal invasion (P=0.031)." (PMID 23902796, 2013). "Here, we report for the first time that DEK transcription is regulated by steroid hormone receptors, particularly ERα in breast cancer, and that DEK expression promotes hormone-dependent cancer cell proliferation." (PMID 23071688, 2012).
cancer (continued). "The gene FBXW7, which is deleted in many of our samples, influences murine intestinal homeostasis and cancer, targeting Notch, Jun, and DEK for degradation." (PMID 22879877, 2012). "DEK, as a proto‐oncogene, plays a crucial role in cancer development." (PMID 39668431, 2025). "DEK protein, a key chromatin regulator, is strongly overexpressed in various forms of cancer." (PMID 38026229, 2023). "Interestingly, DEK is highly overexpressed in numerous forms of cancer, and, in general, its expression is considered an indicator of the cell proliferation level." (PMID 38026229, 2023). "However, a comprehensive understanding of DEK’s cellular distribution and its implications in cancer and cell growth remained elusive." (PMID 38026229, 2023). "It has been reported that DEK silencing may increase cancer cell sensitivity to DOX treatment in nonsmall cell lung cancer and metastatic colorectal cancer." (PMID 35769815, 2022). "RON and DEK are proteins that promote cancer metastasis and synergize mechanistically to activate β-catenin, but the metabolic consequences are unknown." (PMID 36067206, 2022). "DEK has been identified as an oncogene that regulates cellular processes in many types of cancer." (PMID 35742899, 2022). "DEK is a potential biomarker and oncogene, which is reported in many cancers." (PMID 34594378, 2021). "Therefore, DEK over-expression can likely create a pro-tumorigenic microenvironment in Ron-independent cancers as well." (PMID 32708944, 2020). "Several reports have indicated that DEK overexpression leads to aberrant chromatin retention, increased mitotic defects, micronuclei formation, and an increased incidence of hypodiploidy and micronuclei formation in cancer cells." (PMID 32656741, 2020). "DEK is important for DNA repair and preventing apoptosis in cancer cells." (PMID 33304240, 2020). "The human oncoprotein DEK is a unique, non-histone chromatin architectural protein whose deregulated expression is associated with the development of a wide variety of human cancers." (PMID 31408463, 2019). "Our report sheds new light on the still enigmatic molecular functions of DEK and suggests that DEK expression levels may influence the sensitivity of cancer cells to PARP1/2 inhibitors." (PMID 31408463, 2019). "DEK has been investigated as a potential tissue biomarker for many human cancers to date." (PMID 31766266, 2019). "Significantly, this occurs in keratinocytes and SCC cells, suggesting these effects are not dependent upon a cancer cell specific co-variant but are inherent to DEK overexpression." (PMID 28558019, 2017). "Owing to its frequent upregulation in various human malignancies, DEK is thought to have oncogenic activities 30; additionally, targeted suppression of DEK may represent a new strategic approach to the treatment of cancers." (PMID 28834425, 2017). "In conclusion, the presence of TCA cycle intermediates and substantially decreased GSH may be a reflection of the oncogenic effects of DEK specific to cancer cells." (PMID 28558019, 2017). "DEK promotes cancer cell proliferation, thereby enhancing cancer growth." (PMID 28834425, 2017). "Recently, the oncogenic role of DEK has been recognized in several cancer types." (PMID 29228743, 2017). "Additionally, we found that DEK and Skp2 regulation were involved in the mechanisms of these anti-cancer effects." (PMID 28578385, 2017). "Many researchers considered DEK as a candidate anti-cancer target." (PMID 29228721, 2017). "DEK protein degradation can be induced by SPOP and FBXW7-alpha ubiquitin ligases, both of which are tumor suppressors and frequently experience loss-of-function mutations in cancers." (PMID 26425120, 2015).
cancer (continued). "However, the role of DEK in these interactions can also have substantial implications in cancer biology and tumor microenvironments." (PMID 26425120, 2015). "Of future clinical importance, RNA interference-mediated loss of DEK expression causes dramatic apoptosis or senescence of cancer cells whereas differentiated and nontransformed cells remain relatively unharmed." (PMID 26425120, 2015). "In addition to gene amplification and overexpression in cancers, DEK expression and secretion are also induced in response to inflammation." (PMID 26425120, 2015). "DEK, as an oncoprotein, plays an important role in cancer development and progression." (PMID 24650035, 2014). "Subsequently, DEK has been shown to promote tumorigenesis in a variety of cancer cell types, at least in part by its ability to interfere with cell division or DNA repair, inhibit cell differentiation, senescence and apoptosis, and cooperate with transforming oncogenes." (PMID 24353627, 2013). "Therefore, DEK depletion has been suggested as a novel therapeutic method for cancer-targeted therapy." (PMID 23902796, 2013). "Together, our work suggests that, in vivo, hormone signaling, such as 17β-estradiol exposure, might result in the up-regulation of DEK protein levels to promote proliferation in ER+ cancers." (PMID 23071688, 2012). "This transient synthesis of DEK message may explain why microarray studies in Oncomine, using tissues persistently exposed to estrogen, have typically reported lower DEK expression in ER+ cancers when compared to ER- cancers." (PMID 23071688, 2012). "Therefore, when DEK is up-regulated, as is observed in numerous types of cancer including breast cancer, perturbations to normal genome architecture and integrity are likely contributors to oncogenesis." (PMID 23071688, 2012). "The generally increased expression of E2F3 and DEK in the cancer tissues may reflect the latter effect, with further increases in individual cases due to deregulation and copy number gains of these genes." (PMID 15876350, 2005). "Thus, DEK has been suggested as a potential target for cancer treatment." (PMID 39984731, 2025). "Thus, the sequestration of DEK in the TME by PG545 could be another mechanism by which PG545 promotes anti-cancer immunity." (PMID 37550562, 2023). "Importantly, it has been suggested that there might be a large therapeutic window for targeting DEK in cancer treatment, as differentiated epithelial cells are less sensitive than cancer cells to cytotoxic effects of DEK KD." (PMID 37550562, 2023). "DEK, a conserved non-histone chromatin protein, has recognized tumor-promoting properties, its overexpression being associated with poor prognosis in various cancer types." (PMID 37997922, 2023). "We also found that the enrichment score of RSF1 + Macro-C1, NAP1L1 + Macro-C2, and DEK + Macro-C3 clusters have a positive correlation with Cancer immunity cycles score and immunoregulation-related pathways score which indicated a high activity level of all cancer immunity steps." (PMID 38057779, 2023). "Furthermore, the search for CK2 substrates in the CIGB-300 interactome revealed that the peptide is able to interact with substrates playing central roles in cancer cell physiology, such as protein DEK, G3BP1, HDAC2, DNA topoisomerase 1 and 2-alpha, and others with oncogenic potential." (PMID 36672551, 2022). "This suggests that high DEK expression, observed in numerous malignancies including at early stages, may provide the required gains in energy and macromolecule production to enable uncontrolled cancer growth and progression." (PMID 28558019, 2017). "Since hypoxia is a key phenomenon in cancers, we tested whether DEK has a role in regulation of VEGF promoter activity and expression under hypoxic conditions using luciferase reporter assay, real-time reverse transcription-PCR (RT-PCR) and enzyme-linked immunosorbent assay (ELISA)." (PMID 26988756, 2016).
cancer (continued). "This transcriptional regulation may be involved in DEK overexpression in cancer." (PMID 26988756, 2016). "Importantly, the up-regulation of DEK in ER+ and ER- cancers suggest that targeting DEK expression may be a therapeutic option for breast cancers with different molecular signatures." (PMID 23071688, 2012). "In addition, DEK mRNA levels are higher in transcriptionally active and proliferating cells than in resting cells, and elevated mRNA levels are found in several transformed and cancer cells." (PMID 21816114, 2011). "Therefore, the increases in E2F3 and DEK in cultured cancer vs. normal cells may turn out as comparatively moderate." (PMID 15876350, 2005). "To determine if DEK and NUMA1 are involved in the repair of UV-induced DNA lesions, we conducted clonogenic survival assay in multiple cancer cell lines." (PMID 41285742, 2025). "With respect to specific reprogramming based on RON/DEK/β-catenin status, glycolysis and the TCA cycle represent the most canonical and established pathway alterations in cancer." (PMID 36067206, 2022). "DEK have been reported to activate VEGF expression, which play a key role in cancer neoangiogenesis." (PMID 29228721, 2017). "These cancer cells harbor moderate levels of DEK expression when compared to most other HNSCC cell lines, thus allowing for DEK upregulation beyond endogenous levels." (PMID 28558019, 2017). "The fact that both meta-A and meta-B gene sets share DEK, DUSP1 and ITGA6 in common indicates that all three cancer-related genes are more important to look at among all others." (PMID 18605998, 2008). "Even though DEK is overexpressed in a variety of other cancers, there are currently no therapeutic agents that target DEK." (PMID 37550562, 2023). "DEK is an oncogene that promotes proliferation, EMT, and metastasis in various cancers." (PMID 35698073, 2022). "DEK protein was expressed in the nuclei of only 2–3 layers from the basal layer of the non-neoplastic cervical epithelia, and the density of DEK-positive cells was lesser than that in the cancer cells." (PMID 32656741, 2020). "In addition, we also found that DEK knockdown inhibited cell proliferation and metastasis in vivo, suggesting the oncogenic role of DEK in TNBC, consistent with its role in other cancers." (PMID 29228721, 2017). "Most FLAG and PCNA expression was detected in cancer cells, with obvious colocalization, in cancer cells in the tongues of DOX+ iDek mice treated with 4NQO, indicating that DEK may interact with PCNA in cancer cells during tumor progression." (PMID 28834425, 2017). "Consistently, DEK overexpression transforms epithelial cells and promotes cancer in mouse models, whereas DEK knockdown induces cell death in tumor cells but not in differentiated epithelial cells." (PMID 28558048, 2017). "It suggested that the interaction of DEK and WNT pathways may play an important role in multiple types of cancer." (PMID 25544761, 2015). "Importantly, abnormal expression of nucleosome assembly-related genes such as the histone chaperone DEK proto-oncogene (DEK), chromatin assembly factor 1 (CAF-1), and chaperone anti-silencing function 1 (Asf1) were involved in the development of cancers." (PMID 26315111, 2015). "Importantly, DEK depletion by RNAi has been shown to induce a dramatic cytotoxic effect in cancer cells but has relatively little, and no, toxicity in normal and differentiated cells, respectively." (PMID 23071688, 2012). "In this context, the present results showing that PG545 sequesters DEK in the extracellular space, thereby disrupting DEK internalization, nuclear trafficking and interaction with RAD51-containing complexes, might provide a means of targeting this oncoprotein in additional cancers beyond OC." (PMID 37550562, 2023). "Therefore, DEK overexpression in cancer is tumor-promoting, not tumor initiating." (PMID 36275000, 2022).